TNF (tumor necrosis factor)
Diseases named in the same sentence as TNF in open-access papers (continued):
Sharing a sentence is not in itself a finding about the gene and the disease.
Arthritis (continued). "MMPs such as MMP2, MMP3, and MMP9 are up-regulated in arthritis, leading to damage to bones and cartilage of joints via activation of IL1β, TNFα, and many other cytokines." (PMID 37765197, 2023). "Ameliorated the underlying inflammatory response of carrageenan-induced arthritis, which enabled it to be a therapeutic drug for treating arthritis via regulating TNF-α/COX2/MMP9." (PMID 36757520, 2023). "TNF-α is a proinflammatory cytokine that is crucial to the pathogenesis of many inflammatory diseases, such as arthritis." (PMID 37896275, 2023). "It was rather surprising that SF-derived neutrophils are in an inactive state since SF of patients with arthritis contains many neutrophil-activating factors, including TNF and GM-CSF." (PMID 36834478, 2023). "These antibodies enhanced the adhesion between OPN and FLSs, increased the expression of inflammatory cytokines including IL-6, aggravated arthritis, and lowered the retention rate of TNF inhibitors in RA patients." (PMID 36804906, 2023). "The final patient (patient 1) was treated with methotrexate and then a TNF inhibitor, etanercept, and had resolution of arthritis 2 years after the completion of antibiotic therapy." (PMID 37471146, 2023). "While treatment with an anti-TNF antibody only partially reversed gait changes, it was able to fully diminish macroscopic signs of arthritis." (PMID 37869169, 2023). "Previous studies have shown that ozone therapy reduces inflammation as well as IL-1β and TNF-α mRNA levels; ozone decreases oxidative stress in PG/PS-induced arthritis in rats." (PMID 37484853, 2023). "Popliteal lymph nodes (PLNs) from wild-type (n=10) and TNF-Tg male mice with “Early” (5 to 6-months of age; n=6) and “Advanced” (>8-months of age; n=12) arthritis were harvested and processed for spatial transcriptomics." (PMID 37691918, 2023). "TNF-α has been used as an inflammatory marker in arthritis and was correlated to the severity of the disease." (PMID 37798702, 2023). "When serum levels of TNF-α, IL-1 β, and IL-6 were examined in arthritis and normal control rats, there was a significant rise in given proinflammatory cytokines in arthritic disease rats (P < 0.001)." (PMID 37520245, 2023). "Consistent with all of our previous findings, the arthritis control group revealed a significant increase in serum levels of IL-1β, TNF-α, and IL-17 and a significant reduction in the levels of IL-4 in arthritic rats." (PMID 37259429, 2023). "In vivo and in vitro experiments showed that TY dose‐dependently inhibited the proliferation of HFLS‐RA cells induced by TNF‐α, and significantly reduced the paw swelling and arthritis scores in CIA rats." (PMID 38156377, 2023). "After beginning an anti-TNFα treatment (etanercept; dose 25mg 2x per week) in late 2000 she saw a beneficial effect, where her arthritis was reported to be in a much better condition using appropriate metric tests, however her joint inflammation persisted." (PMID 37483613, 2023). "In an arthritis mouse model, PARP inhibition is associated with a reduction in Th1-related cytokines tumor necrosis factor α (TNFα) and IFNγ expression and can inhibit the proliferation of some Th1 cells." (PMID 38111536, 2023). "An extremely important feature of CIA that makes it a valid model for RA is the expression of proinflammatory cytokines, including TNF-α and IL-1β, in the joints of mice with arthritis." (PMID 36674651, 2023). "In the mouse CAIA model, the DPP-1 inhibitor either improved disease parameters or they tended towards improvement; here again, the highest dosage (30 mg/kg/day) yielded the best improvements in arthritis score, rivaling the effect of an anti-TNFα antibody." (PMID 37638021, 2023). "For instance, in this study we demonstrated that daily wheel running, an aerobic weight-bearing activity, indeed exacerbates arthritis in an untreated TNF-Tg model of RA, and arthritic severity is directly correlated with increased activity." (PMID 36732826, 2023).
Arthritis (continued). "In another study using a collagen-induced arthritis model, transfer of IL-32β-producing CD4+ T cells aggravated arthritis, which was attenuated by TNF-α blockade." (PMID 36875066, 2023). "Remarkably, TNF-Tg mice recapitulate the sexual dimorphisms of RA, as females exhibit accelerated onset of arthritis, ILD, and mortality." (PMID 36732826, 2023). "Interleukin-10 (IL-10), IL-1β, mitogen-activated protein kinase (MAPK), IL-6, matrix metalloproteinase-3 (MMP-3), TNF-α and other targets have been confirmed to play important roles in the treatment of arthritis by CC." (PMID 37637408, 2023). "In a murine model of arthritis, GA decreased local inflammation, and inhibited the in vitro release of neutrophil TNF-a." (PMID 36754913, 2023). "When arthritic rats were given Nano ZT/Vit B12, their serum levels of RF, CRP, TNF- α, IL-1β, and IL-17 decreased significantly (p ˂ 0.05) when compared to the arthritis group." (PMID 37259429, 2023). "Studies in mice also showed that activation of FLS is essential for driving arthritis in TNF transgenic mice and collagen-induced arthritis mice." (PMID 37946278, 2023). "With this approach, we evaluated the association of running metrics on the severity of ILD and inflammatory-erosive arthritis in the TNF-Tg mouse model." (PMID 36732826, 2023). "Its expression is induced by proinflammatory factors such as LPS, tumor necrosis factor, and IL-6, as well as chronic inflammatory conditions like hepatitis, arthritis, and MS." (PMID 37409121, 2023). "Chronic exposure to TNF-α promotes the upregulation of sclerostin and in a rat adjuvant-induced arthritis (AIA) model SOST and DKK-1 were overexpressed in the early stages of arthritis onset." (PMID 37887030, 2023). "In a murine model of osteoarthritis, PEMF treatment ameliorated joint pain and arthritis by reducing the proinflammatory cytokines TNF-α and IL-6." (PMID 36674651, 2023). "Together, these data suggest that plasma cell differentiation and IgG2b class-switching in joint-draining lymph nodes are integral to the onset of Advanced arthritis in TNF-Tg mice." (PMID 37691918, 2023). "The combined effect of S100A8, TNF‐α, IL‐1β and IL‐17 induced activated matrix metalloproteinases and exacerbated arthritis." (PMID 37132178, 2023). "In patients with anti-cit-OPN antibodies, it is likely that B cells producing anti-cit-OPN aggravated arthritis, and treatments that target B cells were more effective than treatments that neutralize TNF or target TNF-producing cells." (PMID 36804906, 2023). "Rats with FCA-induced arthritis had significantly higher levels of TNF- α, IL-10, and COX-2 (p < 0.01)." (PMID 38116080, 2023). "MSCs were found to limit the breakdown of proteoglycan in the cartilage of a rabbit arthritis model by decreasing the production of tumor necrosis factor (TNF)-α and MMP-1." (PMID 36829689, 2023). "We observed that TNF-Tg mice with Advanced arthritis showed significantly greater Ighg2b/Ighm expression compared to those with Early arthritis (Early 0.52 ± 0.12 vs Advanced 1.41 ± 0.45 counts/counts, p<0.001)." (PMID 37691918, 2023). "Compared to before treatment, the MRI and clinical manifestations of joint inflammation in children improved after TNF-α inhibition treatment (P < 0.013)." (PMID 37303752, 2023). "In the current study TNF-α was used as an inflammatory marker, where TNF-α is a cytokine that is related to inflammation and tissue degeneration in arthritis." (PMID 37798702, 2023). "TNFAIP3 encodes the (de)ubiquitinating enzyme A20 that inhibits tumor necrosis factor (TNF)-induced activation of nuclear factor kappa-B (NF-κB), and TNFAIP3 gene-deficient mice develop spontaneous arthritis." (PMID 37511889, 2023). "TNF-α, as one of the criteria for the treatment of RA, is also considered one of the key indicators for the treatment of arthritis in advanced AIA rats and OIA rabbits." (PMID 37547331, 2023).
Arthritis (continued). "Using multi-omic spatial and scRNAseq techniques, we identified dynamic changes in the cell populations and their transcriptomic profiles localized to MARCO+ peri-follicular medullary sinuses of TNF-Tg PLNs during the progression of arthritis development." (PMID 37691918, 2023). "The pathogenesis of CFA-induced arthritis includes the release of inflammatory cytokines, such as TNF-α, IL-1, IL-6, prostaglandins, and serotonins, that migrate to the affected area and lead to edema in particular tissues, such as joint capsule and ligaments." (PMID 37305547, 2023). "HlSerpin-a suppressed the production of pro-inflammatory cytokines TNF and IL-6 by LPS-stimulated macrophages and dendritic cells and relieved inflammation in a murine arthritis model." (PMID 36756125, 2023). "Histologic assessments of PLNs from TNF-Tg mice with Early and Advanced arthritis provide insight into the cellular mechanisms mediating these dynamic lymph node changes." (PMID 37691918, 2023). "In an animal model for the treatment of arthritis, matrine inhibited NF-κ B pathway, and TNF and IL-1 β levels were significantly decreased in serum by ELISA." (PMID 36706149, 2023). "In this research, rats treated with indomethacin and NAT showed a significant decrease in elevated TNF-α levels seen in disease control rats, indicating the potential of the plant to reduce arthritis and inflammation." (PMID 38116080, 2023). "In an earlier study, even higher concentrations of TNF were found in SF of different types of arthritis with average TNF levels of 0.97 (±0.6) ng/mL." (PMID 36834478, 2023). "In the LPS-induced acute lung injury model and complete Freund’s adjuvant-induced joint inflammation model, H-PGDS deficiency increased the levels of inflammatory cytokines, including TNFα, IL-1β, and SDF1α." (PMID 37666361, 2023). "This was also seen in a murine model of arthritis, in which TNF blockade was accompanied by an increase in this population." (PMID 36979909, 2023). "TNFα play a major and pivotal role in the development of joint inflammation and skin psoriasis via keratinocyte proliferation and induction of plaque psoriasis." (PMID 36508130, 2023). "We, therefore, examined two independent transgenic mouse arthritis models, the TNFemARE model which is driven by TNF, and the A20myel‐KO model which is driven by IL‐1β." (PMID 37694693, 2023). "Currently, the most recognized are the models of arthritis induced by adjuvant, serum transfer, and tumor necrosis factor." (PMID 36293292, 2022). "In the past, humanized transgenic TNF-α mouse models have been used to overcome these limitations and have proven extremely valuable to understand TNF-α mediated pathologies and to develop novel therapies against arthritis." (PMID 35579886, 2022). "Our data indicated that treatment with ICI successfully induced severe arthritis and pneumonitis in mice, accompanied by a higher frequency of TNF-α+ T cells, particularly in those with collagen-specific antibodies." (PMID 36016934, 2022). "It was demonstrated that the pro-inflammatory cytokines, IFN-γ and tumor necrosis factor (TNF)-α, which are increased in goats with arthritis, activate viral transcription through the GAS and TAS sites." (PMID 35458465, 2022). "For example, in the CIA mouse model and RA patients, the HDAC6 selective inhibitor, CKD-L, inhibits IL-6, TNF-α, and IL-1β expression, and increases IL-10 production, resulting in a decreased arthritis score and inhibited proliferation of effector T cells." (PMID 35453416, 2022). "In particular, IL-6, TNF-α, IL-1β, and IL-8 play a key role in the pathogenesis and development of arthritis, and high levels of these cytokines have been detected in both the serum and the SF of RA, gout, and CPPD patients." (PMID 36361854, 2022). "In arthritis, several cytokines, such as IL-1, IL-6, IL-8, IL-12, IL-17, TNF-α, and IFN-γ, are involved in almost all aspects of articular inflammation and destruction." (PMID 35280697, 2022).
Arthritis (continued). "The declaration of several inflammatory mediators, such as interleukin family and-TNF-α, have been assessed in serum by Trigonella foenum seeds extract in adjuvant-induced arthritis in animal models." (PMID 35889458, 2022). "Treatment with anti-TNF-α significantly mitigated the severity of ICI-related arthritis and pneumonitis by minimizing TNF-α+ T cells in mice." (PMID 36016934, 2022). "Reorganization of the actin cytoskeleton causes the activation of synovial fibroblasts in the modeling of TNF-mediated arthritis." (PMID 35225987, 2022). "Treatment with anti-TNF-α significantly mitigated the severity of arthritis and pneumonitis as well as deposition of collagen in lung of mice." (PMID 36016934, 2022). "Mice with TNF-α induced arthritis were found to have increased circulation of osteoclast precursors, and further was reversed by anti-TNF-α therapy and correlated with systemically increased TNF-α concentrations." (PMID 34991216, 2022). "Blocking TNF-α or IL-6 signaling using neutralizing antibodies alleviated arthritis manifestations in DNase II−/−STINGS365A/S365A mice." (PMID 34901991, 2022). "Intraarticular injection in arthritis and OA patients with TNF- or IL-1 inhibition have been studied although with limited success, possibly due to toxic effects on the chondrocytes." (PMID 36474471, 2022). "To evaluate the therapeutic effect of TNF-α blockade, we treated 5-mo-old DNase II−/−STINGS365A/S365A mice that had already developed arthritis with anti–TNF-α." (PMID 34901991, 2022). "Inhibition of S1P led to decreased serum levels of pro-inflammatory TNF-α, IL-1β, and IL-6 and reduced arthritis activity in previous in vivo experiments, allowing the assumption that S1P is a key regulator of TNF-α stimulated IL-1β and IL-6 release in RA." (PMID 35036874, 2022). "We measured CXCL1, CXCL5 IL-6, IL-8, IL-10, TNFα, and total IgG levels in the aliquots of set 1 and set 2 in eight arthritis patients." (PMID 34998422, 2022). "Both arthritis and uveitis respond well to methotrexate and TNF-a inhibitors (adalimumab and infliximab)." (PMID 35783325, 2022). "Of particular relevance, NOS inhibition is effective in recovering lymphatic contractility in some studies,while recent investigation of global genetic iNOS ablation demonstrated limited effects on lymphatic function and arthritis progression in TNF-Tg mice." (PMID 35882971, 2022). "We used a mouse model of adjuvant-induced arthritis, and at early time-points of the experiment, levels of “classical” pro-inflammatory cytokines, such as IL-1β, IL-6, and TNF, were measured." (PMID 36293292, 2022). "This strategy aimed to determine the effect of specifically blocking the lectin-like domain of TNF released following development of mBSA arthritis." (PMID 36389831, 2022). "One study assessed the safety and efficacy of IA injections with triamcinolone 40 mg or a TNFα inhibitor in 41 PsA patients with mono-arthritis." (PMID 35285486, 2022). "In this case we found that both het and homo Blau KI mice exhibit more severe arthritis than WT littermate mice as evaluated by arthritis score, ankle histology and inflammation score and joint tissue TNF-α mRNA level." (PMID 36189261, 2022). "At the acute inflammatory phase of arthritis, an increase in pro-inflammatory cytokines occurred in aortas as attested by the increased mRNA expression of IL-6, TNF-α, and CXCL-1 (the IL-8 murine equivalent) in AIA." (PMID 35488311, 2022). "It is believed that pro-inflammatory cytokines like tumor necrosis factor α (TNFα) and interleukin 1 (IL-1) are key factors in the development of joint inflammation and clinical symptoms." (PMID 35631676, 2022). "Our study shows that TNFα, a key mediator of inflammation in arthritis, fosters the dynamic regulation of O-GlcNAcylation during osteoclastogenesis." (PMID 35879285, 2022).
Arthritis (continued). "Together with our previous findings, we demonstrate a role of TNF/SOXC molecular axis in FLS during arthritis and suggest its role in the inflammatory pathology of other cell types where SOXC proteins play a vital role." (PMID 35529852, 2022). "A significantly increased plasma TNF-α level was also observed in MBL-/- mice with arthritis compared with WT mice." (PMID 35280697, 2022). "More importantly, treatment with anti-TNF-α significantly mitigated the severity of ICI-related arthritis and pneumonitis, consistent with previous reports." (PMID 36016934, 2022). "By uncoupling the transcriptional cues with the unrealized epigenetic potential of the SFs, we also highlight genes such as Sphk1 and Pla2g2e, the targeting of which had been previously shown to ameliorate modeled TNF-mediated arthritis." (PMID 35879783, 2022). "The authors induced the NET formation in mice with TNFα-induced arthritis and noted the participation of PAD-2 in protein citrullination." (PMID 35886575, 2022). "In an animal study, anti-TNF-α therapy potentially regulated the gut microbiota and intestinal barrier function, and further ameliorated proteoglycan-induced arthritis." (PMID 35197458, 2022). "Nevertheless, IL-1 and TNF-α strongly synergize in numerous biological functions, and simultaneous blockade of IL-1 and TNF-α provides favorable effects in suppressing arthritis development, suggesting the importance of both cytokines." (PMID 35767626, 2022). "Significant increases in all inflammatory markers in MUS-induced arthritis in rats compared to controls, with percentage increases of 678.64, 982.62, and 203.03% for TNF -α, IL-1β and NF-κB, respectively." (PMID 36286462, 2022). "The development of psoriatic lesions and arthritis symptoms in MIP is dependent on cytokines such as TNF-α and IL-17 which get expressed a few days after disease induction." (PMID 35551269, 2022). "hTNF-TG mice overexpressing human TNFα and spontaneously developing arthritis were used to test the treatment effect of penfluridol." (PMID 35045889, 2022). "The control IgG–treated group developed polyarthritis after 10 wk of age, but the anti–TNF-α–treated group was protected from arthritis development." (PMID 34901991, 2022). "To further demonstrate the effects of sCD13 in arthritis, we generated Cd13–/– mice and found that these mice are resistant to development of acute inflammatory arthritis when injected with TNF-α into the knee joints." (PMID 35439173, 2022). "Taking into account all these observations, the results suggest that ozoralizumab was better distributed than adalimumab at the sites of action of arthritis, where TNF-α is abundantly distributed." (PMID 36302840, 2022). "Arthritis is an autoimmune disease characterized by chronic, low-grade inflammation, accompanied by increased inflammatory cytokines (i.e., IL-1β, TNF-α, and IL-6)." (PMID 35280697, 2022). "Further genetic studies in murine arthritis models revealed that TNF signaling in SFs mediates persistent fibroblast activation and promotes pro-proliferative, immune-regulatory, and invasive characteristics." (PMID 35879783, 2022). "Treatment with DAPs in a mouse arthritis model resulted in a significant decrease in TNF-α and neutral endopeptidase activity and relief of arthritis symptoms." (PMID 36235835, 2022). "We are interested in further investigating how TNF-α-secreting T cells contribute to the pathogenesis of ICI-related arthritis and pneumonitis." (PMID 36016934, 2022). "Clinical arthritis scores and the expression levels of proinflammatory cytokines (e.g., IL-17, IL-1β, IL-6, and TNF-α) were significantly attenuated in p40-EBI3-overexpressing and p40-EBI3-Fc-treated mice with CIA compared to vehicle-treated mice with CIA." (PMID 34782759, 2022). "As for TNFR2, mice that lack this receptor develop aggravated arthritis and joint destruction; in addition, TNFR2-deficient mice can also present enhanced osteoclastogenesis, which worsens TNF-α-mediated arthritis." (PMID 36012570, 2022).